ANGPTL8 (angiopoietin like 8)
Diseases named in the same sentence as ANGPTL8 in open-access papers (continued):
Sharing a sentence is not in itself a finding about the gene and the disease.
Graves disease (1 paper, 2019). Graves' disease is an autoimmune disorder that leads to overactivity of the thyroid gland (hyperthyroidism).It is caused by an abnormal immune system response that causes the thyroid gland to produce too much thyroid hormones. "In this study, we aimed to determine the levels of serum ANGPTL8 in normal control subjects and patients with Graves’ disease while further exploring the factors associated with ANGPTL8 levels." (PMID 30900216, 2019). "Further studies are needed to elucidate the mechanisms underlying decreased ANGPTL8 levels in Graves’ disease patients." (PMID 30900216, 2019). "Logistic regression analyses demonstrated that serum ANGPTL8 was significantly associated with Graves’ disease (p < 0.05)." (PMID 30900216, 2019). "Given that ANGPTL8 is attracting ever more attention among researchers in the field of metabolic diseases, we recommend that further studies be conducted to elucidate the role of ANGPTL8 in the development of Graves’ disease." (PMID 30900216, 2019). "Serum ANGPTL8 levels were more significantly decreased in Graves’ disease patients than in healthy control subjects (177.67 ± 135.07 vs 326.41 ± 194.72 pg/mL; p < 0.001)." (PMID 30900216, 2019). "This study measured serum ANGPTL8 levels in patients with Graves’ disease and explored the correlations between its serum levels and thyroid index in Graves’ disease." (PMID 30900216, 2019). "Compared with those in the control subjects, the levels of ANGPTL8 in Graves’ disease patients were significantly decreased (p < 0.001)." (PMID 30900216, 2019). "In this study, we have demonstrated for the first time, to our knowledge, that serum ANGPTL8 concentrations were significantly decreased in Graves’ disease patients compared with the control subjects." (PMID 30900216, 2019). "In summary, our results indicate that circulating ANGPTL8 concentrations were significantly decreased in Graves’ disease patients." (PMID 30900216, 2019). "Logistic regression was used to evaluate the relationship between ANGPTL8 and Graves’ disease." (PMID 30900216, 2019). "Furthermore, the trend in the presence of Graves’ disease was more apparent in the lower serum ANGPTL8 quartile group." (PMID 30900216, 2019). "Investigations need to be carried out into whether the low levels of LDL-C, TC, and APOB in Graves’ disease might be mediated by decreased ANGPTL8 release." (PMID 30900216, 2019). "Circulating concentrations of ANGPTL8 showed a significant reduction in Graves’ disease patients." (PMID 30900216, 2019). "However, little is to date known as to whether circulating ANGPTL8 levels are altered in Graves’ disease." (PMID 30900216, 2019). "ANGPTL8 may hence play a role in the pathogenesis of Graves’ disease." (PMID 30900216, 2019). "Serum ANGPTL8 levels between the two groups were 326.41 ± 194.72 pg/mL for the control group as opposed to 177.67 ± 135.07 pg/mL for the Graves’ disease group." (PMID 30900216, 2019).
hyperlipemia (1 paper, 2021). "ANGPTL8 has been reported to be increased in high fat diet (HFD)-induced diabetic mice, and the overexpression of ANGPTL8 alleviated hyperlipemia, glucose tolerance, IR and inflammation in diabetic mice." (PMID 34163433, 2021).
Jaundice (1 paper, 2024). Yellow pigmentation of the skin due to bilirubin, which in turn is the result of increased bilirubin concentration in the bloodstream. "Among patients without jaundice in the control group, cord ANGPTL8 levels were higher than those in the GDM group (p = 0.029)." (PMID 39770956, 2024).
kidney injury (1 paper, 2021). Trauma to the kidney. "Our data also showed that increases urine ANGPTL8 was associated with indicators of kidney injury." (PMID 33853533, 2021).
lichen planus (1 paper, 2023). A chronic, recurrent, pruritic inflammatory disorder of unknown etiology that affects the skin and mucus membranes. "In this paper we analyzed only ANGPTL8; however, in our earlier study, we took into consideration ANGPTL4 in psoriatic patients, but also in lichen planus and vitiligo." (PMID 36983346, 2023).
liver cirrhosis (1 paper, 2019). "Surprisingly, ANGPTL8 has some molecular interactions with HCC and liver cirrhosis and it has been shown that its expression could be induced by different inflammatory stimuli in HepG2 cells." (PMID 31998458, 2019).
liver inflammation (1 paper, 2024). "Our previous studies revealed that ANGPTL8 promoted high-fat diet-induced liver inflammation and fibrosis through the LILRB2/ERK pathway." (PMID 39019343, 2024).
lung carcinoma (1 paper, 2017). "Similar results were observed in two additional cell lines, HEK293T (a human embryotic kidney cell line) and A549 (a human lung cancer cell line), although their ANGPTL8 level was markedly lower than that of HepG2 cells." (PMID 29255244, 2017).
membranous nephropathy (1 paper, 2021). "Interestingly, the urine ANGPTL8 concentrations in membranous nephropathy and mesangial proliferative glomerulonephritis pathological types were different." (PMID 33853533, 2021).
metabolism (1 paper, 2021). "In addition to TG, different studies have suggested the correlation between ANGPTL8 and TC, LDL and HDL, indicating that there is an inseparable relationship between ANGPTL8 and lipid metabolism, as well as diseases characterized by disorder of lipid metabolism." (PMID 34582711, 2021).
pancreatic cancer (1 paper, 2023). "ANGPTL8 attenuated the apoptosis of pancreatic cancer cell by down-regulating Bcl-2." (PMID 37294581, 2023).
peripheral arterial disease (1 paper, 2023). A disorder of the arteries supplying the upper and lower extremity and the visceral organs. "Studies have shown that serum ANGPTL8 levels are positively correlated with the severity of coronary artery disease (CAD) and peripheral arterial disease." (PMID 37294581, 2023).
renal carcinoma (1 paper, 2021). A carcinoma arising from the epithelium of the renal parenchyma or the renal pelvis. "Based on its association with a poor outcome, ANGPTL8/betatrophin may serve as a novel unfavorable prognostic marker in renal cancer." (PMID 34646087, 2021). "The Pathology Atlas in the HPA database points out that ANGPTL8/betatrophin is an unfavorable prognostic marker in renal cancer." (PMID 34646087, 2021).
renal fibrosis (1 paper, 2025). A final common manifestation of a wide variety of chronic kidney diseases characterized by glomerulosclerosis and tubulointerstitial fibrosis. "Based on single‐cell transcriptomics and untargeted metabolomic sequencing analysis of mice with NAFLD and renal fibrosis, we predicted that the liver excretory protein ANGPTL8 acts as a bridge in the progression of kidney fibrosis exacerbated by NAFLD." (PMID 40995682, 2025). "Given the significant correlation between NAFLD and renal fibrosis, we propose the central hypothesis that ANGPTL8 derived from NAFLD activates the ALOX5AP pathway in renal CCR2+PIRB+ macrophages via PIRB, reprogramming linoleic acid metabolism, and driving profibrotic inflammation." (PMID 40995682, 2025). "It is demonstrated that NAFLD exacerbates renal fibrosis, as HFD‐induced hepatocytes release significant levels of ANGPTL8, which activates renal CCR2+PIRB+ macrophages." (PMID 40995682, 2025). "Thus, the ANGPTL8/PIRB/ALOX5AP axis is a crucial signaling pathway between the liver and kidneys, and CCR2+PIRB+ macrophages play a pivotal role in the progression of NAFLD‐induced renal fibrosis." (PMID 40995682, 2025).
vitamin D deficiency (1 paper, 2020). A nutritional condition produced by a deficiency of VITAMIN D in the diet, insufficient production of vitamin D in the skin, inadequate absorption of vitamin D from the diet, or abnormal conversion of vitamin D to its bioactive metabolites. "They revealed the positive correlation between the level of vitamin D and ANGPTL8, so the vitamin D deficiency was associated with a lower level of ANGPTL8." (PMID 32537470, 2020).
metabolic disorders (26 papers, 2018 to 2025). "Numerous studies have demonstrated that ANGPTL8 holds potential as a biomarker for metabolic disorders and associated diseases." (PMID 37767256, 2023). "Overall, the results of the pathway analysis identifies important signaling pathways and associated co-expressed genes with ANGPTL8 which should be investigated further for their mutual and individual role in pathogenesis of DM and related metabolic disorders." (PMID 30627105, 2018). "ANGPTL-8, a factor involved in regulating lipid and glucose metabolism, serves as a potential biomarker for metabolic diseases." (PMID 41026696, 2025). "ANGPTL8 has been shown to have a critical role in different systemic disorders, such as metabolic disorders, cardiovascular diseases and cancer." (PMID 36983346, 2023). "Several studies have reported that ANGPTL8 acts as a key modulator in lipid metabolism and metabolic disorders." (PMID 37947641, 2023). "The role of ANGPTL8 in metabolizing lipids and glucose and in metabolic disorders and inflammation is widely recognized." (PMID 37755252, 2023). "The ANGPTL8 (Angiopoietin-like protein 8) gene is an important regulator of metabolic disorders, blocking ANGPTL8 in mice promoted triglyceride clearance, energy expenditure, and weight loss." (PMID 36922782, 2023). "Angiopoietin-like protein 8 (Angptl8) is a novel important regulator in metabolic disorders, and plays a crucial role in lipid metabolism." (PMID 35565941, 2022). "The changes of circulating levels of ANGPTL8 in metabolic disorders, including T2DM, imply its potential value in the diagnosis of these diseases." (PMID 34582711, 2021). "Of course, in order to understand the role of ANGPTL8 in metabolic disorders, some suggestions must be made." (PMID 34582711, 2021). "These contradictory results lead to different opinions on the role of ANGPTL8 in metabolic disorders." (PMID 34582711, 2021). "Elevation of Angptl8 levels in circulation has been recently considered as a potential biomarker for metabolic diseases." (PMID 31470507, 2019). "Whether ANGPTL8 interacts with PirB and acts as a pro‐ or anti‐inflammatory factor and whether circulating ANGPTL8 exerts extracellular functions in metabolic diseases remain controversial." (PMID 37481670, 2023). "While the significance of this finding is yet to the elucidated, further investigation may be necessary for ANGPTL8 as a potential predictor of postdelivery maternal metabolic disorders." (PMID 35529083, 2022). "Therefore, it is necessary to conduct a comprehensive analysis on the regulation, physiological and pathological functions of ANGPTL8, so as to infer the role of ANGPTL8 in metabolic disorders related diseases." (PMID 34582711, 2021). "In other metabolic diseases, the circulation level of ANGPTL8 also changed to some extent." (PMID 34582711, 2021). "Angptl8 has been shown to play critical roles in the development of various metabolic diseases." (PMID 31388006, 2019). "Also, alteration of ANGPTL8 concentration in metabolic diseases including diabetes, obesity, and MtS has been revealed by many epidemiological studies." (PMID 31998458, 2019). "ANGPTL8 levels progressively decrease from PCOS patients with MetS to those without MetS and may be a serum marker associated with the degree of metabolic disorders." (PMID 31346314, 2019). "Therefore, the association between ANGPTL8 and glucose, adiposity, ADI, and IR parameters confirmed the potential role of ANGPTL8 in metabolic disorders and IR and thus contributed to the occurrence and development of MetS." (PMID 31346314, 2019). "Briefly, the investigation of predominant functional roles, biological processes, and associated signaling molecules (receptors/cofactors/genes) of ANGPTL8 is of immense importance for its assessment as a molecular target for the treatment of DM and related metabolic disorders." (PMID 30627105, 2018).
metabolic disorders (continued). "Research regarding the effects of ANGPTL8 on thermogenic machinery and metabolic regulation during the fetal–neonatal transition may shed light on the approaches to neonatal hypothermia and metabolic disorders." (PMID 29719529, 2018). "In addition, many previous studies showed the steady involvement of ANGPTL8 in metabolic disorders." (PMID 40725697, 2025). "Angiopoietin-like protein 8 (ANGPTL8), a newly identified hormone, has been recently characterized as a metabolic regulator which can affect energy homeostasis and has interesting potentials as a metabolic disease therapy." (PMID 30900216, 2019). "The current study focused on ANGPTL8 in pregnant women with or without metabolic disorders." (PMID 35529083, 2022).
cancer (13 papers, 2016 to 2025). A tumor composed of atypical neoplastic, often pleomorphic cells that invade other tissues. "The current study sought to identify high-risk, “non-synonymous, single-nucleotide polymorphisms” (nsSNPs) in both ANGPTL3 and ANGPTL8 to evaluate the role that these nsSNPs play in various types of cancer." (PMID 37375208, 2023). "Dysregulated expression of ANGPTL3 and ANGPTL8 was associated with poor prognosis in cancer patients." (PMID 37375208, 2023). "Increasing evidence suggests that ANGPTL8 is associated with cancer development and prognosis." (PMID 38107478, 2023). "ANGPTL8 gene expression and the association with prognosis in different cancers." (PMID 38107478, 2023). "However, ANGPLT8 levels and the association between ANGPTL8 and prognosis also differ among various cancers." (PMID 38107478, 2023). "The number of cancer-causing high-risk SNPs was lower in ANGPTL8 (n = 4) than in ANGPTL3 (n = 7)." (PMID 37375208, 2023). "Seven high-risk SNPs in ANGPTL3 and four in ANGPTL8 were predicted to be involved in cancer." (PMID 37375208, 2023). "The current study’s findings indicate that ANGPTL3 and ANGPTL8 proteins are tumor suppressors and are aberrantly expressed in various types of cancer." (PMID 37375208, 2023). "Survival rate analysis indicated that both upregulation and downregulation of ANGPTL3 and ANGPTL8 leads to low survival rates in various types of cancer." (PMID 37375208, 2023). "Third ANGPTL8 negatively regulates inflammation and autophagy by inhibiting NF-κB activation, which was confirmed to be crucial to the progression of cancer." (PMID 38107478, 2023). "Our findings indicate that ANGPTL3 and ANGPTL8 play a pivotal role in cancer progression by interacting with tumor-suppressor proteins such as ITGB3, ITGAV, RASSF5, and FNDC5." (PMID 37375208, 2023). "We believe that the comprehensive analysis of nsSNPs in ANGPTL3 and ANGPTL8 represents a significant advancement in our understanding of these proteins and their role in cancer." (PMID 37375208, 2023). "We further found that ANGPTL1, ANGPTL3, ANGPTL4, and ANGPTL8 were significantly highly expressed in HCC cell lines than other types of cancer cell lines (p < 0.05)." (PMID 35692877, 2022). "In contrast to previous studies, ANGPTL8 promoted endothelial barrier dysfunction and proliferation in cancer." (PMID 35851270, 2022). "In the present work, we performed comprehensive analyses of the expression profiles and the correlation between the expression and prognostic value of the liver-derived metabolic regulator ANGPTL8/betatrophin in different cancers." (PMID 34646087, 2021). "In the DriverDBv3 database, different expression levels of ANGPTL8/betatrophin was found across 33 cancer types." (PMID 34646087, 2021). "Second, The current study only focused on the bioinformatics analysis of the prognostic role of ANGPTL8/betatrophin in cancers." (PMID 34646087, 2021). "The angiopoietin-like protein (ANGPTL) family members, except for the novel atypical member ANGPTL8/betatrophin, have been reported to participate in angiogenesis, inflammation and cancer." (PMID 34646087, 2021). "In the GEPIA database, different expression levels of ANGPTL8/betatrophin were observed across 33 cancer types." (PMID 34646087, 2021). "The importance of NF-κB signaling in cancer development and the link between inflammation and cancer are well understood, however, the role and mechanism of ANGPTL8/betatrophin in cancers need to be further studied." (PMID 34646087, 2021). "In tumor vs. normal samples, the gene expression of ANGPTL8/betatrophin showed great difference in several cancer types including BRCA, CHOL, LUAD, LUSC, UCEC, and KIRC." (PMID 34646087, 2021). "The toxicity effect of ANGPTL8 on HepG2 cancer cells was time independent and by increasing the concentration of ANGPTL8 the viability of the cells was reduced slightly." (PMID 31998458, 2019).
cancer (continued). "In the case of HCC, the mRNA expression profile of ANGPTL8 is concordant with the α-fetoprotein gene, which is an HCC-associated gene and diagnostic and prognostic biomarker of this cancer in several liver cancer cell lines." (PMID 31998458, 2019). "Overall, the current study revealed that both ANGPTL3 and ANGPTL8 constitute potential prognostic biomarkers for cancer; moreover, nsSNPs in these proteins might lead to the progression of cancer." (PMID 37375208, 2023). "Moreover, we identified eleven high-risk nsSNPs that cause various types of cancer: seven candidates for ANGPTL3 (L57H, F295L, L309F, K329M, R332L, S348C, and G409R) and four candidates for ANGPTL8 (P23L, R85W, R138S, and E148D)." (PMID 37375208, 2023). "However, the protein expression of ANGPTL8 displayed opposite results in ccRCC/KIRC samples from patients in different cancer stages, years old age groups and weight categories." (PMID 38107478, 2023). "However, in the future, in vivo studies should be conducted to validate the significance of the correlation of these SNPs in ANGPTL3 and ANGPTL8 with a specific type of cancer." (PMID 37375208, 2023). "However, more detailed studies must be conducted to unravel the exact molecular aspects of ANGPTL8 role in cancer pathways." (PMID 31998458, 2019). "ANGPTL8/betatrophin may be a promising prognostic biomarker and therapeutic target, thus providing evidence to support further exploration of its role in defined human cancers." (PMID 34646087, 2021). "Therefore, the role of ANGPTL8 in lipid metabolism might also contribute to cancer or other detrimental outcomes." (PMID 32732946, 2020). "Most importantly, the biological functions of ANGPTL8/betatrophin are not fully clarified, and further studies on its role in cancer progression, especially KIRC, UCEC, SARC and PCPG, should be performed in the near future." (PMID 34646087, 2021). "The potential mechanism of ANGPTL8 in cancers has not yet reached a consensus." (PMID 38107478, 2023). "ANGPTL8 expression in human cancer has not been reported yet." (PMID 29389861, 2018). "However, we do not know whether the atypical ANGPTL family member ANGPTL8/betatrophin also plays a role in human cancers." (PMID 34646087, 2021). "With regard to the protein expression profile of ANGPTL8/betatrophin in the UALCAN-CPTAC dataset, no expression information was available across 7 cancers except for clear cell renal cell carcinoma (ccRCC)/KIRC." (PMID 34646087, 2021).
cardiovascular disease (9 papers, 2018 to 2024). "(iii) Single-nucleotide mutation of ANGPTL8 has been proved to be associated with the risk of T2DM and cardiovascular disease." (PMID 34582711, 2021). "This indicated that ANGPTL3, ANGPTL4, and ANGPTL8 play important role in cardiovascular disease through regulation of lipid metabolism." (PMID 32440963, 2020). "Furthermore, it was reported that targeting ANGPTL8 with antisense oligonucleotide (ASO), a second-generation 2-O-methoxyethyl ASO against ANGPTL8, could prevent cardiovascular disorders." (PMID 32746907, 2020).